PPARG (peroxisome proliferator activated receptor gamma)
Diseases named in the same sentence as PPARG in open-access papers (continued):
Sharing a sentence is not in itself a finding about the gene and the disease.
atherosclerosis (continued). "This review will summarize the transcriptional target genes regulated by PPARγ in SMCs and outline the therapeutic implications of PPARγ activation for the treatment and prevention of atherosclerosis and its complications." (PMID 18288288, 2008). "PPARα and PPARγ agonists can ameliorate chronic inflammatoryconditions, such as atherosclerosis, arthritis, and inflammatory bowel disease." (PMID 18551186, 2008). "Previous studies in two murine models of atherosclerosis have shown that treatment with PPARγ agonists protected against the development of atherosclerosis." (PMID 18302760, 2008). "Ingeneral, PPARγ activationattenuates endothelial dysfunction and the development of atherosclerosis." (PMID 17710111, 2007). "PPARG expression is upregulated in atherosclerosis (AS) mouse models compared to normal controls." (PMID 41465406, 2025). "PPARγ activation is essential for maintaining cholesterol homeostasis by promoting cholesterol efflux from macrophages, which is a key step in preventing foam cell formation and the development of atherosclerosis." (PMID 40867523, 2025). "Furthermore, PPARγ, a key protein involved in macrophage lipid metabolism, is an important target for plant-derived substances that mitigate atherosclerosis." (PMID 40099271, 2025). "Moreover, PPARγ inhibits inflammatory processes, exhibits anti-atherosclerosis activity, and improves heart performance." (PMID 39595621, 2024). "However, medium-chain structured lipids ameliorate high-fat diet-induced atherosclerosis potentially by reducing the expression of PPARγ." (PMID 38699583, 2024). "Notably, Bu-Shen-Kang-Shuai formula and Tan-Yu-Tong-Zhi formula ameliorate atherosclerosis potentially via promoting macrophage polarization towards an M2 phenotype through activation of PPARγ and downregulation of NK-κB." (PMID 38699583, 2024). "HDAC inhibitors also protect against atherosclerosis by enhancing the expression of PPARG." (PMID 39595621, 2024). "Furthermore, Saikosaponin A and ginsenoside 20(R/S)-Rg3 act as natural PPARγ activators, ameliorating hyperlipidemia and atherosclerosis." (PMID 38699583, 2024). "As opposed to control wild-type (WT) mice, PPARγ/ApoE double knockout mice obtained more severe lesions associated with atherosclerosis, indicating PPARγ′s role in AS." (PMID 39524227, 2024). "Moreover, glycine can increase β-oxidation activity by activating the PPARγ signaling pathway and has anti-atherosclerosis and anti-inflammatory properties." (PMID 38785939, 2024). "In vivo and ex vivo experiments were conducted to figure out whether NOB inhibits lipid uptake and the progression of atherosclerosis by modulating the PPARG/CD36 signaling pathway." (PMID 38468335, 2024). "Fourth, both activation and inactivation of PPARβ and particularly PPARγ may achieve similar therapeutic effects, suggesting some complex regulatory mechanisms are involved in PPARs' therapy of atherosclerosis." (PMID 38699583, 2024). "According to the KEGG research findings, the pathways of AA for the treatment of AS primarily involve lipid metabolism-related signals (lipids and atherosclerosis and PPARγ signaling pathways) and inflammatory response-related signals (IL-17 and TNF signaling pathways)." (PMID 39065817, 2024). "Nobiletin alleviates atherosclerosis by inhibiting lipid uptake via the PPARG/CD36 pathway." (PMID 38468335, 2024). "PPARγ has been shown to play an important role in vascular protection, whereas its activation suppresses the oxidative stress and apoptosis of endothelial cells, protects against vascular thrombosis, and alleviates atherosclerosis." (PMID 36841479, 2023). "In addition, the role of PPARγ signalling for improving atherosclerosis is partly dependent on LXRα induction and NF‐κB inhibition." (PMID 37905351, 2023).
atherosclerosis (continued). "According to previous studies, PPARγ, which is essential for macrophage polarization, is involved in regulating of M1-type macrophage polarization to M2-type in inflammation and injury-related diseases, such as Parkinson’s disease, sepsis, and atherosclerosis." (PMID 37501214, 2023). "PPARγ is hyperacetylated in aging, and consistently, the metabolic protections of PPARγ deacetylation are exaggerated in aged 2KR mice, such as the inhibition of visceral adiposity and protection against atherosclerosis." (PMID 37408258, 2023). "Desumoylation at K107 in PPARγ may inhibit serum-stimulated VSMCs proliferation, might play an important role against atherosclerosis." (PMID 35309069, 2022). "Therefore, the functional regulation of PPARγ is of very important for the prevention and treatment of atherosclerosis." (PMID 35309069, 2022). "Our results show that AG may regulate NF-κB/CEBPB/PPARG signalling to play a therapeutic role in atherosclerosis." (PMID 35543243, 2022). "Three key pathways (pathways in cancer, the TNF signaling pathway, and lipid and atherosclerosis) and the top six anti-COVID-19 core targets (IL-6, PPARG, MAPK3, PTGS2, ICAM1, and MAPK1) were determined to be involved in the treatment of COVID-19 with active phytomolecules of Kochiae Fructus." (PMID 35992697, 2022). "Furthermore, PPARγ has been proved to be beneficial for the heart, whose activation or upregulation can attenuate diabetic cardiomyopathy, atherosclerosis, hypertension, and heart failure." (PMID 35402529, 2022). "The currently found SPPRAMs that associated with atherosclerosis mainly consists of three types: partial PPARγ agonist, dual PPAR α/γ agonist, and non-agonist PPARγ ligand." (PMID 35309069, 2022). "The downregulation of PPARG in SMC increases pro- inflammatory factors such as MMP and OPN, thereby promoting SMC proliferation, migration, and vascular remodeling, which is associated with atherosclerosis." (PMID 35990982, 2022). "PPARG constitutes heterodimer with retinoid X receptor and thus conducts transcription of multiple genes, which mainly regulates adipocyte differentiation and is related to cancer, inflammation, and atherosclerosis." (PMID 35037412, 2022). "PPARγ has emerged as one of the most promising therapeutic targets for cardiovascular complications, and its synthetic ligands, such as Thiazolidinediones (TZDs) have also been shown to have anti-atherosclerosis function." (PMID 35309069, 2022). "Research about the effects of AG on PPARG activation focusses chiefly on lipid metabolism and the inflammatory response, which may be more closely related to atherosclerosis." (PMID 35543243, 2022). "However, a study in a mouse atherosclerosis model revealed that PPARγ knockout mice exhibited enlarged atherosclerotic plaques, which is related to the suppression of ABCG1 expression." (PMID 35432274, 2022). "Collectively, it is widely believed that activation of PPARγ can moderately lower blood pressure and plays a protective role in endothelial dysfunction, vascular inflammation, and other pathological processes that lead to atherosclerosis." (PMID 36359869, 2022). "Subsequently, we confirmed in vivo that QHZYF could attenuate atherosclerosis in ApoE−/− mice and regulate the expression levels of related molecules in PPARγ/LXRα/ABCA1-ABCG1 and PPARγ/NF-κB p65 pathways of ApoE−/− mice and C57BL/6 wild-type mice." (PMID 36518993, 2022). "Based on these results, we found that QHZYF might attenuate atherosclerosis via targeting PPARγ-mediated PPARγ/LXRα/ABCA1-ABCG1 and PPARγ/NF-κB p65 pathways to regulate cholesterol efflux and endothelial inflammation." (PMID 36518993, 2022). "Therefore, manipulating PPARγ acetylation is a promising therapeutic strategy to anti-atherosclerosis." (PMID 35309069, 2022). "PPARγ is ligand-inducible transcription factor that is highly expressed in macrophages, controlling macrophage inflammation, polarization, and lipid metabolism in atherosclerosis plaques." (PMID 35590369, 2022).
atherosclerosis (continued). "PPARγ plays a crucial role in anti-atherosclerosis by promoting cholesterol efflux, inhibiting monocytes infiltrating into the vascular intima under endothelial layer, and inhibiting their transformation into macrophages, inhibiting VSMCs proliferation and migration." (PMID 35309069, 2022). "Therefore, PPARγ is considered as a therapeutic target in CVDs such as atherosclerosis and heart failure, and its activators have been tried to be used as potential strategy for CVD treatment." (PMID 35402529, 2022). "In this review, we focus on the significance of PPARγ activity regulation (PTMs and SPPARMs) in the occurrence, development and treatment of atherosclerotic diseases, and further clarifies the value of PPARγ as a therapeutic target for anti-atherosclerosis." (PMID 35309069, 2022). "M2 macrophages have been shown to exert an inhibitory effect on the development of atherosclerosis, and the inclination of macrophages toward the M2 type as a result of PPARγ activation by 12-HEPE may be one mechanism suppressing the onset of atherosclerosis." (PMID 34001916, 2021). "Moreover, PPARγ regulates the inflammatory involvement of the immunogenicity of dendritic cells observed in atherosclerosis." (PMID 35111067, 2021). "Curcumin, an active ingredient in curcuma rhizomes, inhibits M1 macrophage polarization and the production of pro-inflammatory factors via TLR4/MAPK/NF-κB pathways, and induces M2 macrophage polarization via activating PPARγ, contributing to an anti-atherosclerosis effect." (PMID 34026849, 2021). "A number of studies also provide evidence for an inhibitory role of PPARγ in atherosclerosis and that it may exert atheroprotective effects." (PMID 34966435, 2021). "Similarly, Ginsenoside Rg3 alleviates atherosclerosis via reversing M1 polarization to M2 polarization in a PPARγ-dependent mechanism." (PMID 34026849, 2021). "PPARγ is known to be one of the central links of alternative macrophage activation, and macrophage polarization is a critical process in atherosclerosis development and regression." (PMID 34966274, 2021). "However, the disruption of PPARγ negative regulation in mice leads to aggravation of atherosclerosis development." (PMID 34440119, 2021). "The positive effects of PPARγ in atherosclerosis may occur due to its anti-inflammatory effects in the vasculature." (PMID 33322009, 2020). "According to the activation of PPARγ signaling pathway, emodin could also alleviate atherosclerosis followed by promoting cholesterol efflux or play other roles though regulating inflammatory response and nitric oxide production." (PMID 33415161, 2020). "What is more, endothelial PPARγ is an indispensable factor to prevent endothelial dysfunction with aging, and interference with PPARγ function can accelerate vascular aging and atherosclerosis." (PMID 32655760, 2020). "Upregulation of DNMT1 correlates with decrease in peroxisome proliferator-activated receptor gamma (PPAR-γ) and with the increased production of pro-inflammatory cytokines in peripheral blood monocytes isolated from patients with atherosclerosis and in macrophages from adipose tissue." (PMID 32486098, 2020). "Subsequently, the respective roles of Wingless/Int-1 (WNT)- and Peroxisome proliferator-activated receptor γ (PPARγ) signaling in atherosclerosis and VC will be explained before discussing existing knowledge about their interplay as well as its relevance for VC." (PMID 33322009, 2020). "Activation of PPARγ is a promising strategy for the prevention and treatment of atherosclerosis." (PMID 33959213, 2020). "The expression of PPARγ in macrophages is closely related to atherosclerosis." (PMID 31998284, 2019). "In summary, hydroxy-α-sanshool (HAS) could play a significant role in improving the lipid profile and may act as a protective agent against atherosclerosis by regulating of PPARγ and APOE to reduce lipid peroxidation." (PMID 31534622, 2019).
atherosclerosis (continued). "TNFα and PPARγ are important modulators of metabolism, inflammation, and atherosclerosis." (PMID 31275366, 2019). "A study analyzing the human arterial tissue proteomics identified several vascular and plasma biomarkers related to early atherosclerosis including TNF-α, insulin receptor, PPARα, and PPARγ protein networks, predictors of both development and site of atherosclerosis and CVD." (PMID 31354915, 2019). "Furthermore, Dnmt1, a maintenance enzyme responsible for de novo methylation, regulates the methylation status of the PPARγ promoter in macrophages, where more Dnmt1 correlates with less PPARγ gene expression levels in atherosclerosis patients’ monocytes." (PMID 30283300, 2018). "As activators of the nuclear receptor PPAR-γ, TZDs might inhibit atherosclerosis through PPARγ-dependent and PPARγ-independent mechanisms." (PMID 29084546, 2017). "Therefore, by modulating LXR-driven ABCA1 gene expression through the SHC1/PI3K/AKT/PPARγ/LXRα axis, LRP1 is presenting itself as a pivotal regulator of the metabolic as well as inflammatory processes underlying atherosclerosis." (PMID 29144234, 2017). "VSMC-specific PPARγ-deficient mice show accelerated atherosclerosis, which is not inhibited by pioglitazone administration." (PMID 27703271, 2016). "PPARδ may serve as a more potent therapeutic target than PPARγ in atherosclerosis or inflammatory therapy, and the potency of 1 μM PPARδ is similar to that of 10 μM PPARγ in anti-inflammatory effect." (PMID 26884762, 2016). "Second, PPARG suppresses atherosclerosis while TR4 enhances atherosclerosis." (PMID 25859557, 2015). "PPARγ, monocyte adherence and lipid uptake have roles in atherosclerosis." (PMID 25426628, 2014). "On one hand, PPARγ agonists reduce atherosclerosis in human patients and animal models." (PMID 25371662, 2014). "Furthermore, recent findings supporting a role of PPARγ in inflammation and cell growth have promoted the investigation of PPARγ agonists as experimental drugs for some chronic diseases such as atherosclerosis and cancer, among others." (PMID 23630612, 2013). "PPARγ is a ligand-activated nuclear transcription factor that plays important roles in cellular differentiation, cancer, inflammation, insulin sensitization, atherosclerosis, and metabolic diseases." (PMID 23199346, 2012). "PPARγ is a ligand-activated nuclear transcription factor involved in cellular differentiation, cancer, inflammation, insulin sensitization, atherosclerosis, and metabolic diseases, and it has been shown to inhibit NF-κB and to play important roles in several inflammatory processes." (PMID 23199346, 2012). "In addition, the Pro12Ala polymorphism was regarded to change the response of synthetic PPARγ agonists– thiazolidinediones (TZDs) treatment, which seemed to improve the insulin resistance and limit atherosclerosis development." (PMID 23300871, 2012). "PPARγ has recently been highlighted as an important determinant of macrophage phenotype and function, which may explain the favourable effect of PPARγ modulation in experimental atherosclerosis." (PMID 21526997, 2011). "Additionally, it was shown that bone marrow transplantation of PPARγ−/− cells worsened the outcome of atherosclerosis, strongly suggesting a role for PPARγ in macrophages involved in lesion formation." (PMID 21382489, 2011). "15d-PGJ2 is a ligand of PPARγ, which acts to atherosclerosis formation." (PMID 22003398, 2011). "However, PPARγ- C161→T markedly correlated with severity of atherosclerosis in patients with CAD with T2DM, which is through a mechanism underlying an altered lipid, but not glucose, metabolism." (PMID 20334678, 2010).
atherosclerosis (continued). "Furthermore, upregulation of 15-LOX-1 is linked to the characteristic feature of early atherosclerosis and elevated synthesis of 13-HODE, which in turn enhances the expression of CD36 and FABP4 via PPAR-γ activation (13-HODE PPARγ-agonist) and triggers apoptosis." (PMID 39599599, 2024). "Notably, Qing-Xue-Xiao-Zhi formula (QXXZ, 清血消脂方), Si-Ni decoction (四逆汤), Qi-Shen-Yi-Qi Pill (芪参益气丸), and Yin-Xing-Tong-Mai decoction (银杏通脉汤) have been demonstrated to attenuate hyperlipidemia and atherosclerosis by facilitating RCT through upregulation of PPARγ–LXRα–ABCA1/ABCG1 signaling pathways." (PMID 38699583, 2024). "Loss of Ash2l abundance at the promoter of PPARγ inhibited CD36 transcription, which significantly weakened the proximity ligation signals between TLR4 and CD36, thus reducing NF-κB signal activation and contributing to the protection against endothelial injury and atherosclerosis." (PMID 38280036, 2024). "Therefore, we speculated that oridonin might affect atherosclerosis against lipid and inflammation pathways, in which LXRα, NF‐κB and PPARγ might have a vital role." (PMID 37905351, 2023). "PPARγ is mainly expressed in adipocytes, monocytes/macrophages, the liver, skeletal muscle and the heart, and it has been suggested to mediate adipogenesis and be related to ectopic lipid accumulation, such as that occurring in liver steatosis, cardiac lipotoxicity and atherosclerosis." (PMID 37432260, 2023). "However, there is considerable evidence showing unfavorable effects of PPARγ on foam cell formation and atherosclerosis via the transcriptional activation of CD36 and its positive correlation with ectopic lipid accumulation, including that observed in atherosclerosis." (PMID 37432260, 2023). "Nevertheless, targeting PPARγ sumoylation may provide a novel mechanism for anti-atherosclerosis." (PMID 35309069, 2022). "However, miR-19b may target and modulate other genes in addition to PPARγ, and these interactions may also play a role in advancing atherosclerosis." (PMID 35656103, 2022). "AG may regulate NF-κB/CEBPB/PPARG signaling to alleviate atherosclerosis." (PMID 35543243, 2022). "Additionally, PPARγ exerts anti-inflammatory effects in several types of tissues and organs by repressing the expression and function of pro-inflammatory factors such as NF-κB and Nrf2/CREB and it is implicated in cancer and atherosclerosis." (PMID 33799988, 2021). "This means that even if macrophages have aggregated as a result of adipocyte hypertrophy, the secretion of anti-inflammatory cytokines such as adiponectin promoted by the PPARγ-mediated actions by ligands such as 12-HEPE may prevent the subsequent development of atherosclerosis." (PMID 34001916, 2021). "In human atherosclerotic lesions, PPARγ activation has been reported to promote differentiation of proatherogenic M1 macrophages into an alternative anti-inflammatory phenotype, M2, which could protect against the development of atherosclerosis." (PMID 34966435, 2021). "Therefore, already registered PPARγ agonists may deserve more attention as potential VC inhibitors for patients at the onset of atherosclerosis due to their anti-inflammatory and cell fate modulating properties." (PMID 33322009, 2020). "PPARγ agonists can downregulate the Wnt/beta-catenin pathway, which is involved in inflammation, endothelial dysfunction, the proliferation of vascular smooth muscle cells, and vascular calcification, therefore PPARγ agonists might be therapeutic targets for the treatment of atherosclerosis." (PMID 32106617, 2020). "Hypercholesterolemia- (HC-) induced endothelial dysfunction is the first step of atherogenesis, and the peroxisome proliferator-activated receptor γ (PPARγ (PPARγ (PPARγ) has been reported to attenuate atherosclerosis formation; however, the underlying mechanisms are not fully understood." (PMID 32190383, 2020).